HGF (hepatocyte growth factor)
Diseases named in the same sentence as HGF in open-access papers (continued):
Sharing a sentence is not in itself a finding about the gene and the disease.
tumor (continued). "c-Met activation, through its ligand HGF, can lead to tumor growth, invasiveness, and metastasis." (PMID 22419847, 2012). "HGF treatment rescued EGFR inhibited tumor cells, indicating that pathways similar to those present in the NMuMG and MCF-10A mammary cells may also be used by cancer cells to sustain their growth." (PMID 23028720, 2012). "In addition, CAFs produce multiple growth factors [e.g. insulin growth factor (IGF), hepatocyte growth factor (HGF)], which promote tumor cell proliferation, survival and motility/migration." (PMID 22408128, 2012). "As HGF in the paracrine loop also stimulates Ln5-γ2 expression, inhibition of the HGF-c–Met pathway may suppress tumour invasion promoted via both paracrine and autocrine loops." (PMID 21829200, 2011). "To test whether cancer cells instruct surrounding fibroblasts to secrete factors such as HGF to promote tumor growth, we co-cultured NAF #200N with MDA-MB-468 cells using a transwell insert containing a 0.4-μm polyester membrane." (PMID 21249190, 2011). "As both OSM and HGF are likely to be relatively ubiquitous in the tumor microenvironment, it is possible they may work to promote early invasion and metastasis of OSA cells in vivo." (PMID 21481226, 2011). "Indeed, heparin-binding proteins such as VEGF, FGF2, SDF-1α, HGF and P-selectin have been shown to mediate angiogenesis, tumor and host cell trafficking, tumor cell mobility and tumor cell seeding." (PMID 21698156, 2011). "Nk4 (also known as IL32b) inhibits HGF-c-Met signalling and therefore tumour metastasis." (PMID 21172020, 2010). "Increasing evidence has demonstrated that the HGF/c-Met signaling pathway could be another valuable pathway for research on tumor target therapy, besides the VEGF signal pathway." (PMID 20667141, 2010). "A higher tumor K-ras mutation rate was observed with L2G7 alone compared to controls, suggesting that agents targeting HGF may be less effective against mutated K-ras lung tumors." (PMID 21390244, 2010). "This indicates that the HGF/c-Met signaling pathway might be involved in the rapid progression of residual tumor after RFA." (PMID 20667141, 2010). "Notably, in tumor sections, the HGF positive cells were limited to the epithelial compartment, suggesting that HGF in the colon is a marker of an intact normal epithelium, and is down-regulated during the inflammatory response." (PMID 21059221, 2010). "In sum, our data show for the first time that a novel, 20-amino-acid peptide derived from the β chain of human Fgn, has a unique ability to inhibit the angiogenic responses of ECs to multiple GFs such as VEGF, FGF2, PDGF and HGF in vitro, and to inhibit tumour vascularisation in vivo." (PMID 20068569, 2010). "The c-Met protein is expressed mostly in in mammalian tissues and plays an important role in different cellular process; its ligand is the HGF (Hepatocyte Growth Factor), known also as Scatter Factor (SF) and c-MET over-expression or inactivation is implicated in different tumoral disease." (PMID 19949545, 2009). "Cytokines, such as TGF-β, HGF, and fibroblast growth factor, may stimulate tumor invasion metastasis via PKC and MAP kinase." (PMID 19497102, 2009). "We hypothesized that HGF-mediated uPA upregulation is responsible for the invasive properties of tumor cell phenotypes, and consequently blocking uPA activity could be a potential target in inhibiting tumor cell invasion." (PMID 19497102, 2009). "The metastatic behaviour of tumour cells is regulated by extracellular growth factors such as hepatocyte growth factor (HGF), a ligand for the c-Met receptor tyrosine kinase, and aberrant expression/activation of the c-Met receptor is closely associated with metastatic progression." (PMID 19272140, 2009).
tumor (continued). "Growth factors stain in patches that do not correlate with the more sparse staining patterns of the TAF markers themselves due to the fact that the tumor cells also secrete the growth factors HGF, IL-6 and EGF in the presence of MSC as demonstrated by in vitro co-culture data." (PMID 19352430, 2009). "Thus, because Spint1 and Spint2 serve to inhibit the activity of HGF, these genes have been characterised as tumour suppressors." (PMID 18506145, 2008). "Hepatocyte growth factor is known to play a number of roles in cancer metastasis and tumour growth." (PMID 18506145, 2008). "Besides VEGF binding, a novel mechanism was recently proposed for NRP1 to promote tumour progression through the enhancement of autocrine hepatocyte growth factor/scatter factor signalling through c-Met." (PMID 18781179, 2008). "Therefore it is widely accepted that pro-angiogenic factors, such as VEGF165 and HGF, have higher expression in the surrounding tissues than in tumor tissues." (PMID 17608955, 2007). "Thus, the combination of co-expression of HGF and its receptor, overexpression of the HGF receptor, and elevated levels of bioactive HGF in the tumour or circulation, or both, are frequent events in malignancies." (PMID 17576468, 2007). "The c-Met protein is expressed mostly in in mammalian tissues and plays an important role in different cellular processes; its ligand is the HGF (Hepatocyte Growth Factor), known also as Scatter Factor (SF) and c-MET over-expression or inactivation is implicated in different tumoral disease." (PMID 19384429, 2007). "These pathways lead to the various effects of HGF on diverse cell- and tumour-type combinations." (PMID 17576468, 2007). "Interestingly, HGF and its receptor, when co-expressed in the same cancer cells, predict a more virulent and aggressive tumour type 10." (PMID 17576468, 2007). "HGF can promote cell adhesion by up-regulating CD44 in tumor cells and our data suggest that a similar relationship may exist in the testis." (PMID 16336681, 2005). "In order to identify common growth factor-responsive genes, which may represent candidate genes of tumour growth regulation in general, we compared gene expression induced by gastrin, HGF, EGF and PACAP." (PMID 15846300, 2005). "Therefore, the HGF/c-Met pathway plays an important role during tumour progression in a paracrine pattern and/or autocrine pattern." (PMID 15083185, 2004). "However, the Ki-67 proliferation index was 59.9±24.5 among stromal HGF-positive tumours, and 41.2±31.4 among stromal HGF-negative tumours." (PMID 15083185, 2004). "However, few studies on NSCLCs have evaluated both HGF and c-Met expression, and distinguished tumour cell derived-expression from stromal cell-derived expression." (PMID 15083185, 2004). "Therefore, we undertook this study using immunohistochemistry to investigate the relationship between the HGF/c-Met pathway and both tumour growth and angiogenesis." (PMID 15083185, 2004). "For example, the HGF antagonist NK4 suppresses tumour growth and could improve the clinical outcome of patients with carcinomas that exhibit overexpression of HGF and/or c-Met." (PMID 15083185, 2004). "Importantly, IF cells secreted a factor inducing HGF production in fibroblasts and the factor was identified as interleukin-1, which means that a mutual interaction exists between tumour cells and fibroblasts, as mediated by the HGF/HGF-inducer loop." (PMID 10468286, 1999). "DARPins binding to tumor-associated molecular targets such as human epidermal growth factor receptor 2 (HER2), epithelial cell adhesion molecule (EpCAM), epidermal growth factor receptor (EGFR), vascular endothelial growth factor (VEGF) and hepatocyte growth factor (HGF) have been described." (PMID 40445498, 2025). "Our results may uncover an aspect of tumor microenvironment regulation involving CAFs and HGF." (PMID 41048570, 2025).
tumor (continued). "After a durable clinical and radiographic response, the progression biopsy demonstrated loss of MET amplification together with emergent HGF p.G401A and NF1 p.M546L, pointing to ligand reactivation and RAS/MAPK bypass as hypothesis-generating routes of escape in this tumor." (PMID 41268440, 2025). "As a mesenchymal marker in the tumor microenvironment, HGF’s high expression is associated with reduced Cyt c release and caspase-3 activity in TNBC, suggesting that inhibition of the mitochondrial apoptosis pathway is an important mechanism for HGF to promote cancer." (PMID 40860340, 2025). "Interestingly, hyaluronan and HGF were tumor-promoting in myCAFs." (PMID 40677714, 2025). "DARPins binding to such tumor-associated molecular targets, such as human epidermal growth factor receptor 2 (HER2), epithelial cell adhesion molecule (EpCAM), epidermal growth factor receptor (EGFR), vascular endothelial growth factor (VEGF), and hepatocyte growth factor (HGF) have been described." (PMID 40508045, 2025). "This correlation may be attributed to various factors, including the immunosuppressive properties of neutrophils, their ability to promote tumour growth and their facilitation of tumour cell migration and invasion through the release of hepatocyte growth factor (HGF) and other molecules." (PMID 39228012, 2024). "Similarly, the HGF-MET pathway has been implicated in promoting T-cell exhaustion through the activation of downstream signaling pathways, such as PI3K/AKT and MAPK/ERK, which are involved in maintaining the immunosuppressive tumor microenvironment." (PMID 39484036, 2024). "However, the origin of hepatocyte growth factor present in the tumour microenvironment is unknown as it may be synthesised by a variety of tissues throughout the body, including liver or adipose tissue." (PMID 38290287, 2024). "Due to the significant variation in tumor characteristics and immune status among different patients, future research needs to develop personalized treatment plans and identify reliable biomarkers to accurately assess the function of the HGF/c-MET axis in each patient." (PMID 39201787, 2024). "Moreover, single-cell analysis of circulating tumor cells has unveiled compelling insights into the effectiveness of HGF/c-MET inhibitors, such as rilotumumab (formerly AMG102) and compound A (a c-MET small molecule inhibitor), in curtailing cancer progression post-surgery." (PMID 39664377, 2024). "Consequently, HGF expression by tumour cells or by the tumour microenvironment could be an attractive biomarker for predicting MET activation and thus its sensitivity to targeted therapies, even in the context of MET mutation." (PMID 38652103, 2024). "Mechanistically, tumor cells may induce CAFs to produce HGF through the production of lactate." (PMID 39201787, 2024). "On the one hand, the primary tumor sample displayed the highest number of genes having a great overlap with those already reported to be associated with MPNST, such as the MET Proto-Oncogene, Receptor Tyrosine Kinase (MET), the Hepatocyte Growth Factor (HGF), and others." (PMID 39409151, 2024). "Thus, while tumor cells may chemotax along these HGF gradients alone, co-migrating with macrophages greatly supports their ability for sustained directional migration and extends the chemoattractive influence of the blood vessels." (PMID 39555068, 2024). "However, in most cases, HGF/c-MET signaling inhibits CTL-mediated tumor killing." (PMID 39201787, 2024). "Importantly, the HGF/c-MET signaling pathway is also instrumental in tumor immune escape." (PMID 39201787, 2024). "In addition, MerTK signaling promotes the secretion of anti-inflammatory cytokines, such as transforming growth factor-β (TGFβ), hepatocyte growth factor (HGF), and IL-10, resulting in immunosuppressive, pro-tumor, M2-polarized macrophages in the tumor microenvironment (TME)." (PMID 38443968, 2024).
tumor (continued). "Previous studies have reported that blocking VEGF/VEGFRs signaling may lead to hypoxia in the tumor microenvironment by inhibiting angiogenesis, resulting in activation of HGF/MET axis, which conferred drug resistance and increased local invasion and distant metastasis." (PMID 39354638, 2024). "For example, the roles of HGF and ROS, secreted from neutrophils, were examined, and their promotion role in tumor evolution was verified, further suggesting neutrophil plasticity could be co-opted as a breakthrough in tumor therapy." (PMID 38244071, 2024). "In addition, the intracellular Fe3+ release from HGF also strengthened tumor ferroptosis." (PMID 37984863, 2024). "Finally, upregulation of TGF-β pathway by HGF leads to tumor EMT and invasion." (PMID 36959792, 2023). "It has been reported that elevated MDSCs could contribute to tumor progression by remodeling TME through autocrine and paracrine, and a number of soluble factors secreted by MDSCs, such as IL-6, IL-23, HGF, and VEGF, in various tumors including CRC were associated with poor chemotherapeutic effect." (PMID 37781363, 2023). "In addition, a high level of HIF-1α after incomplete LITs also contributed to the elevated expression of HGF in the residual tumor, but HGF could in turn synergize with HIF-1α to promote tumor progression." (PMID 36831664, 2023). "Some neutrophil populations, known as tumor-associated neutrophils (TANs), promote cancer cell growth, invasion, and angiogenesis by producing matrix metalloproteinase-9 (MMP9), vascular endothelial growth factor (VEGF), and hepatocyte growth factor (HGF) at primary and metastatic sites." (PMID 37644235, 2023). "Consistent with our observation that tumor-stroma interactions reflected activation of fibroblast cells and prior reports demonstrating that HGF secretion is predominantly attributed to stromal cells, HGF transcription was significantly correlated with tumor-stroma interaction." (PMID 36647832, 2023). "Consequently, patients with KRAS mutation may exhibit a reliance on MET signaling, specifically downstream of HGF, which is secreted by non-tumor cells and remains undetected under 2-D monolayer culture conditions." (PMID 37381723, 2023). "Unlike propofol, sevoflurane exposure resulted in bigger tumour size, shorter survival time (assessed with the clinical endpoints, including body weight loss > 20% and tumour volume > 70 mm3), higher HGF, HIF1α, IL1β and TNFα expressions, and lower E-cadherin and TIMP-2 expressions." (PMID 35953652, 2023). "Therefore, the study have shown that the stromal cells of PCa may form an autocrine c-Met loop, which may act together with HGF expressed by cancer cells to promote tumor progression." (PMID 36959792, 2023). "Examples of cytokine-receptor pairs implicated in MSC tumour tropism are SDF-1 & C-X-C motif chemokine receptor-4 (CXCR4), VEGF & VEGFR, MCP-1 & C-C motif chemokine receptor (CCR2), epidermal growth factor (EGF) & EGFR, and hepatocyte growth factor (HGF) & c-Met." (PMID 35103937, 2022). "However, miR-101, miR-206, and miR-26a target c-Met/HGF and inhibit tumor growth and metastasis." (PMID 35986321, 2022). "Limitation of this approach, precluding its clinical translation, could be due to the concomitant presence of endogenous HGF that will induce the classical biological effects of the HGF, that is, cell proliferation/survival, and could also promote tumor growth." (PMID 35292998, 2022). "In addition, higher levels of vascular endothelial growth factor (VEGF) and hepatocyte growth factor (HGF) in exosomes derived from heparanase high expressing cells are in comparison with heparanase low expressing cells, and better mediate spreading of tumour cells and invasion of endothelial cells." (PMID 35454762, 2022).
tumor (continued). "Aberrant activation of the MET/HGF pathway is involved in the development and metastatic progression of various tumors, and this pathway constitutes the mechanism by which cancer patients acquire resistance to targeted treatment and attenuates tumor response to immunotherapy." (PMID 36341335, 2022). "However, other pro-angiogenic factors could be produced by the tumor or by cells from the tumor microenvironment such as Hepatocyte Growth Factor (HGF)." (PMID 34771724, 2021). "Hence, GCMSCs-derived HGF promoted tumor proliferation by upregulating c-Myc-HK2 in vivo." (PMID 33718248, 2021). "In addition, this study showed that MPM cell lines stimulate fibroblast motility and growth on the one hand and fibroblasts vice versa stimulate MPM growth and motility by HGF on the other hand, indicating an important cross-talk and tumor promoting symbiosis of CAFs and MPM cells." (PMID 33562138, 2021). "In addition, we found that high HGF expression was associated with smaller tumor size and inferior TNM stage but was not related to other clinical parameters or OS in OSCC patients." (PMID 34970484, 2021). "Therefore, apart from the successful anti-tumor immune stimulation, HGF may inhibit the systemic metastasis of hypermetastatic B16F10 cancer effectively." (PMID 34593794, 2021). "Moreover, the tumor environment has an important effect on maintenance of cancer stemness in some studies, such as hepatocyte growth factor, which is secreted by myofibroblasts in tumor micro-environment and can induce stemness features in colorectal cancer cells by improving Wnt activity." (PMID 34381360, 2021). "Therefore, HGF/c-Met signaling has become one of the most popular targets for tumor treatment." (PMID 34970484, 2021). "Next, we examined whether LY294002 could abolish HGF-mediated tumor growth in vitro." (PMID 33500715, 2021). "In addition to promoting tumor cell proliferation, CAFs have also been shown to increase the stem cell-like properties of cancer cells, particularly through secretion of growth factors such as HGF." (PMID 33808627, 2021). "Cell surface nucleolin serves as a binding partner of different molecules (as P-selectin, hepatocyte growth factor or pleiotrophin), thus mediating their biological activities, such as cell differentiation, adhesion and leukocyte trafficking, inflammation, angiogenesis and tumor development." (PMID 34207464, 2021). "Furthermore, a high level of VEGFA in HCC cells could lead to excessive production of hepatocyte growth factor (HGF), which induces tumor cell proliferation." (PMID 34680462, 2021). "Moreover, HGF enhances the migration and invasive capacity of tumor cells." (PMID 34408780, 2021). "Our results demonstrated that the HGF/c-MET pathway could affect tumor proliferation and invasion." (PMID 34261467, 2021). "Hence, signaling pathways activated by HGF-c-Met might be useful targets in the prevention of tumor progression." (PMID 34572344, 2021). "Furthermore, downstream activation of AKT and ERK by HGF was apparently not affected by abemaciclib, suggesting that a different compensatory mechanism might exist in the HGF-rich tumor microenvironment, and might play a prominent role in hepatic metastasis." (PMID 33806615, 2021). "Further studies are necessary to elucidate the role of these signaling pathways in vivo as the tumor microenvironment may be involved in the production and/or the effects of CCL20, HGF and MSP through cells such as macrophages, cancer-associated fibroblasts, and myofibroblasts." (PMID 34853656, 2021). "In addition, SNAIL was identified as a crucial factor involved in PI3K-AKT signaling and the EZRIN-RHO pathway that may be regulated by SDF-1 and HGF, factors that promote tumor cell metastasis." (PMID 32664538, 2020). "Moreover, the intact and normal HGF/c-Met signaling is elementary for sustaining normal redox homeostasis and could suppress tumor in the N-nitrosodiethylamine-induced HCC." (PMID 32117981, 2020).